C4B (complement C4B (Chido/Rodgers blood group))
Diseases named in the same sentence as C4B in open-access papers (continued):
Sharing a sentence is not in itself a finding about the gene and the disease.
cataract (2 papers, 2023 to 2024). Partial or complete opacity of the crystalline lens of one or both eyes that decreases visual acuity and eventually results in blindness. "In contrast, within the female samples, two complement proteins showed significant upregulation in the POAG group compared to cataracts: C4B (FC = 1.56, p = 0.030) and F2 (FC = 1.37, p = 0.007)." (PMID 37763167, 2023). "In African Americans with POAG, five complement proteins were significantly elevated in the AH samples compared to those with cataracts: C4A (FC = 2.33, p = 0.027), C4B (FC = 1.69, p = 0.015), complement component C7 (FC = 1.38, p = 0.025), F2 (FC = 1.31, p = 0.023), and C3 (FC = 1.21, p = 0.027)." (PMID 37763167, 2023). "The ratios of aqueous humour/plasma of C1q, C4, C4b, C3b/iC3b, C5, CFB, CFD, CFI, and CFH in the RVO patients were significantly higher than those in the cataract patients." (PMID 39587546, 2024). "Surprisingly, we detected positive correlations between plasma and aqueous levels of four complement proteins (C4b, C3b/iC3b, CFD, and CFI, r = 0.57 ~ 0.74) in cataract patients, but only one (i.e., CFI, r = 0.609) in RVO patients." (PMID 39587546, 2024). "Whereas, within the female cohort, two complement proteins (C4B and F2) were upregulated and one (C8G) downregulated in the POAG samples when compared to cataracts." (PMID 37763167, 2023). "The plasma levels of C4b, C3b/iC3b, and CFD positively correlated with their counterparts in the aqueous humour in cataracts but not in RVO patients." (PMID 39587546, 2024).
colon carcinoma (2 papers, 2020 to 2022). "The PPI network showed that CD55 and the key complement system components C3, C4A, and C4B are closely related to colon cancer." (PMID 36741376, 2022).
colorectal cancer (2 papers, 2020 to 2022). A primary or metastatic malignant neoplasm that affects the colon or rectum. "In general, in colorectal carcinoma progression, C4B, MBL2, CARD9, and TNFRSF8 affected DSS." (PMID 35456394, 2022).
Dengue (2 papers, 2019 to 2020). "Our data also indicate that the levels of C2, C4b, C5, C5a, C9, factor D and factor I are significantly associated with clinical parameters, especially with platelet counts, of dengue patients." (PMID 32913345, 2020). "We measured the levels of MBL and the complement proteins C2, C4b, C5, C5a, C9, adipsin (factor D) and factor I in serum samples of dengue and DWS patients and healthy controls." (PMID 32913345, 2020). "In conclusion, our study shows that MBL2 polymorphisms are associated with dengue in a Vietnamese study group and that C2, C4b, C5, C5a and factor D levels are significantly modulated in dengue patients and during the progression of dengue." (PMID 32913345, 2020). "The levels of the complement proteins C2, C4b, C5, C5a, C9, factor D and factor I are modulated in dengue patients during the clinical course of dengue." (PMID 32913345, 2020). "In dengue patients, C2 levels correlated with the levels of C4b, C5, C5a and factor D (Spearman’s rho = 0.5, 0.39, 0.61, − 0.25; P < 0.0001, < 0.0001, < 0.0001 and = 0.0002, respectively)." (PMID 32913345, 2020).
encephalitis (2 papers, 2021 to 2025). An acute inflammatory process affecting the brain parenchyma. "Fourth, in East-Asian subject E133P with anti-NMDA receptor encephalitis, the C4B gene had a mutation that changed tryptophan-660 to a stop-codon (W660x), which was present in a haplotype with HLA-DRB1*04:06 and B*15:27." (PMID 34764957, 2021). "While initially discovered in an encephalitis patient, the W660x mutation in C4B gene is modestly prevalent among East-Asians." (PMID 34764957, 2021). "The direct cytotoxicity of complement activation has been demonstrated in patients with GAD-Ab-associated encephalitis, who exhibited increased transcriptional levels of complement protein genes (C3, C4A, C4B) and elevated levels of activated complement proteins in the CSF." (PMID 41041342, 2025). "Among them are a subject with fast-migrating C4B that is detectable in many individuals of European ancestry, and three different cases of C4B deficiencies in healthy subjects and patients with SLE or anti-NMDAR encephalitis." (PMID 34764957, 2021).
inflammatory bowel disease (2 papers, 2024 to 2025). A spectrum of small and large bowel inflammatory diseases of unknown etiology. "A study on pediatric inflammatory bowel disease indicated that individuals with low C4B copy numbers had milder inflammation and higher gut microbial diversity compared to those with high C4B copy numbers." (PMID 41346597, 2025). "A study investigated the influence of C4B gene number on gut microbiota and in vitro serum complement activation in patients with paediatric inflammatory bowel disease (PIBD)." (PMID 38464719, 2024).
nephritis (2 papers, 2021 to 2023). Inflammation of renal tissue. "Using mass spectrometry, we found an increase in the level of complement components C3, C4b, C5, C9, and CFB in the urine of patients with active nephritis." (PMID 37108355, 2023).
Obesity (2 papers, 2023 to 2025). Accumulation of substantial excess body fat. "In concrete, proteomic analysis revealed higher abundance of four complement system proteins—C3, C4b, C8, and CFH, in cats with obesity." (PMID 39795034, 2025).
pneumonia (2 papers, 2016 to 2020). An acute, acute and chronic, or chronic inflammation focally or diffusely affecting the lung parenchyma, caused by an infection in one or both of the lungs (by bacteria, viruses, fungi, or mycoplasma.). "In this experiment we demonstrate that severe pneumonia in rats is associated with complement activation in the lungs, measured by increased levels of complement C4b/c." (PMID 27683129, 2016). "Pneumonia resulted in augmented levels of C4b/c in BALF increasing over time." (PMID 27683129, 2016). "BALF levels of C5a, C3b/c and C4b/c were neither different between patients with or without ARDS, nor between patients with or without pneumonia." (PMID 33336309, 2020). "Median BALF levels of C5a, C3b/c, and C4b/c, and the effects of VT and ΔP on those levels, were not different between patients with or without ARDS, and in patients with or without pneumonia." (PMID 33336309, 2020).
prion disease (2 papers, 2020 to 2021). A transmissible disease that is caused by a protein that is able to induce abnormal folding of normal cellular proteins, leading to characteristic spongiform brain changes, which are associated with neuronal loss without an inflammatory response. "Furthermore, the expression of A1-associated gene C4b was also elevated in PLX5622-treated mice during prion disease at this early time point." (PMID 32381108, 2020).
pulmonary tuberculosis (2 papers, 2014 to 2020). A bacterial infection that affects the lungs and is caused by Mycobacterium tuberculosis. "Clinical data of 187 cases of pulmonary tuberculosis (PTB) were analyzed using statistical methods, while serum levels of complement C4b (C4b), fibronectin (FN), and prolidase (PEPD) were detected using the ELISA method among the control, minimal PTB, moderate PTB, and advanced PTB groups." (PMID 24484408, 2014).
retinal degeneration (2 papers, 2023 to 2024). Degeneration of the retina. "The C4 cleavage fragment C4b (not to be confused with the mouse C4b gene) can contribute to opsinization of OS, and C4b knockeout partially inhibits PR loss in the mouse sodium iodate (NaIO3) model of retinal degeneration." (PMID 38528525, 2024).
Sjogren syndrome (2 papers, 2020 to 2024). An autoimmune disorder in which immune cells attack and destroy the glands that produce tears and saliva. "Notably, mutations in the genes encoding C2, C3, C4A, C4B have been linked to SLE, and Sjogren’s syndrome has been reported in patients with genetic deficiencies in C1q, C4, and C2." (PMID 32514272, 2020).
adenovirus infection (1 paper, 2019). "Covalent coupling of C4b to the viral capsid interferes with the carefully orchestrated stepwise uncoating process that is essential for adenovirus infection." (PMID 30926239, 2019).
age-related macular degeneration (1 paper, 2023). Age-related loss of vision in the central portion of the retina (macula), secondary to retinal degeneration. "C4b was previously defined an aging-induced gene and implicated in age-related macular degeneration." (PMID 37943864, 2023).
Arterial thrombosis (1 paper, 2019). The formation of a blood clot inside an artery. "The abundance of the fast-reacting C4B could aggravate the pathogenic process in arterial thrombosis." (PMID 31134052, 2019). "The higher level of C4 protein in arterial thrombosis was mainly attributable to higher C4B (p = 2.1 × 10−5)." (PMID 31134052, 2019).
cholangiocarcinoma (1 paper, 2015). A carcinoma that arises from the intrahepatic biliary tree (intrahepatic cholangiocarcinoma) or from the junction, or adjacent to the junction, of the right and left hepatic ducts (hilar cholangiocarcinoma). "Fourteen proteins (6%) were identified as more abundant in cholangiocarcinoma, including such proteins as intercellular adhesion molecule 1, ceruloplasmin, haptoglobulin, complement c3, and -c4b." (PMID 25304323, 2015).
coagulopathy (1 paper, 2025). "Remarkably, main hub proteins in the CR group were VTN, C3, C4B, C9, and CFH that play a major role in the complementary pathway, which has gained increased attention as a major contributor to cancer‐related coagulopathy." (PMID 40079446, 2025).
colitis (1 paper, 2024). Inflammation of the colon. "Conversely, Arhgef2 deficiency causes susceptibility to colitis, expressed as increased pathology score, increased production of inflammatory cytokines (IL6, MCP1, RANTES, C4b), increased infiltration of CD45+ cells in the lamina propria, with a marked abundance of CD11b+/Ly6G+ neutrophils." (PMID 38200184, 2024).
depression (1 paper, 2020). "Third, we found that the plasma proteins GSN and C4B were biomarkers of depression, similar to findings in previous studies using the same LC-MS platform." (PMID 33126421, 2020).
dyslexia (1 paper, 2016). A learning disorder characterized by an impairment in processing written words. "A C4B null allele, a deficient form of the HLA C4B gene (no C4B protein produced), was reported to be more frequent in ASD, ADHD and dyslexia." (PMID 31557990, 2016).
frontotemporal dementia (1 paper, 2024). Frontotemporal dementia (FTD) comprises a group of neurodegenerative disorders, characterized by progressive changes in behavior, executive dysfunction and language impairment, as a result of degeneration of the medial prefrontal and frontoinsular cortices. "When NPTX2 is overexpressed in neurons in the Tau P301S model of frontotemporal dementia (FTD) and Alzheimer’s Disease (AD), the level of the complement C4b and synapse engulfment decreases, leading to increased number of excitatory synapses on parvalbumin interneurons." (PMID 39258226, 2024).
Granuloma (1 paper, 2014). A compact, organized collection of mature mononuclear phagocytes, which may be but is not necessarily accompanied by accessory features such as necrosis. "Our study showed that C4b, FN, and PEPD are associated with tissue damage, granuloma formation, and cavity formation, respectively, in patients with PTB." (PMID 24484408, 2014). "C4b may be associated with tissue damage, while FN and PEPD are associated with granuloma and cavity formation, respectively." (PMID 24484408, 2014).
IgA nephropathy (1 paper, 2025). "Therefore, we hypothesize that C4A and C4B genes may influence the occurrence and development of IgA nephropathy by regulating complement activation and immune complex metabolism." (PMID 40149558, 2025).
immune complex diseases (1 paper, 2022). "Studies have shown that C4B genetic defects are associated with human immune complex diseases." (PMID 36548652, 2022).
leptospirosis (1 paper, 2012). A contagious bacterial infection caused by spirochetes of the genus Leptospira. "The LigB interactions with C3b and C4b involve repeats 9 to 11, the region found to be important in fibronectin and fibrinogen binding, suggesting the use of an adaptable binding domain that serves multiple functions in the pathogenesis of leptospirosis." (PMID 22911815, 2012).
Mitral stenosis (1 paper, 2014). An abnormal narrowing of the orifice of the mitral valve. "This may be the reason for the lower abundances of C3, C4A, C4B and C4b binding protein α chain observed in Mitral Stenosis patients." (PMID 25379033, 2014).
myocarditis (1 paper, 2021). Myocarditis is a condition that is characterized by inflammation of the heart muscle (myocardium). "In contrast, the plastic caging significantly increased the expression of CD11b/CR3 (p = 0.002), C4b (p = 0.002), and the mast cell anaphylatoxin complement receptor C5aR1 (p = 0.006) in males during acute myocarditis compared to glass caging." (PMID 34445539, 2021).
myopia (1 paper, 2023). "When comparing the aqueous humour complement levels between the two groups, all components of the CP (C1q, C2, C4 and C4b) and the common pathway (C3, C3b/iC3b and C5) were significantly higher in the high-myopia group." (PMID 37448698, 2023). "In this study, we detected significantly higher intraocular levels of complement proteins involved in the classic pathway (C1q, C2, C4 and C4b) and alternative pathway (CFB, CFI, C3b/iC3b) in human eyes with high-myopia or with pathological myopia." (PMID 37448698, 2023).
pancreatic ductal adenocarcinoma (1 paper, 2019). An infiltrating adenocarcinoma that arises from the epithelial cells of the pancreas. "The C4B level was of moderate diagnostic utility in terms of pancreatic ductal adenocarcinoma diagnosis (AUC = 0.860), serving as a novel serum biomarker for detecting early stage disease." (PMID 31040200, 2019).
periodontal disease (1 paper, 2021). "For example, the complement components C4A and C4B highly expressed in periodontal disease were found to modulate T cell immune response by stimulating the activation and migration of T cells." (PMID 33869630, 2021).
preeclampsia (1 paper, 2011). Preeclampsia is a hypertensive disorder of pregnancy that is characterized by new-onset hypertension with proteinuria presenting after 20 weeks of gestation, and depending on mild or severe forms may initially present with severe headache, visual disturbances, and hyperreflexia. "Because SLE is characterized by autoantibodies that trigger the classical pathway, defective regulation of C4b is likely to influence the severity of tissue injury and risk for preeclampsia." (PMID 21445332, 2011).
proliferative diabetic retinopathy (1 paper, 2011). Advanced retinopathy due to diabetes mellitus characterized by the formation of new vessels in the retina. "Activation of the complement pathway has been demonstrated by increased protein expression of several factors such as C3, C4b, C9 and factor B in the vitreous of diabetic patients with proliferative diabetic retinopathy." (PMID 22046295, 2011).
protein deficiency (1 paper, 2021). "This is a typical example to account for C4B protein deficiency because no C4B structural gene was present." (PMID 34764957, 2021).
renal cell carcinoma (1 paper, 2025). "Although there are no experimental prognostic studies on these hubs in BLCA, a study on renal cell carcinoma (RCC) found that C4B suppression was associated with increased survival in patients receiving cytokine therapy, and a deficiency of C4B in stage IV RCC patients was linked to better survival." (PMID 40283026, 2025).
Ss (1 paper, 2024). "Our data here clearly shows that there is a link between lower levels of C1q, C4b, MBL, C5a, C3, C3b/iC3b factor B and factor D and the presence of Ss infection." (PMID 38564496, 2024).
tauopathy (1 paper, 2018). Neurodegenerative disorders involving deposition of abnormal tau protein isoforms (tau proteins) in neurons and glial cells in the brain. "Interestingly, the expression changes of genes such as Gfap, Csf1, Prnp, C4b and Trem2, identified with 2 m Tau hippocampi (GSE107183) have been observed at symptomatic stages in the same rTg4510 tauopathy model in other studies." (PMID 29915328, 2018).
thoracic aortic aneurysm (1 paper, 2025). An aneurysm formed in the wall of the proximal portion of the descending aorta proceeding from the arch of the aorta. "Moreover, in our work, we have shown that SMCs isolated from the tunica intima actively secrete proteins C3 and C4B, therefore, it can be assumed that the classical and alternative pathways of the complement system are activated with thoracic aortic aneurysm." (PMID 40695950, 2025).
thromboses (1 paper, 2021). "Intriguingly, among patients with SLE or antiphospholipid antibodies, those with relatively higher C4 protein levels or with high copy-number of C4B genes are associated with increased risk for chronic hypertension and thromboses." (PMID 34764957, 2021). "In a cross-sectional study of human subjects with antiphospholipid (aPL) antibodies, those with median and high copy number of C4B (≥2) are strongly associated with thromboses and recurrent pregnancy loss (RPL) for female subjects." (PMID 34764957, 2021).
tuberculosis (1 paper, 2025). A chronic, recurrent infection caused by the bacterium Mycobacterium tuberculosis. "Of identified core proteins, complement factor H formed a diagnostic classifier that distinguished latent Mtb infection from healthy controls with good performance, and we also identified C4B, MBL2, SAA1, and matrix Gla protein as potential proteomic signatures of active tuberculosis." (PMID 40736242, 2025).
uveitis (1 paper, 2023). An inflammatory process affecting a part of or the entire uvea. "AAV2-IBI302 (bispecific anti-VEGF and anti-C3b/C4b FcFP, Innovent Biologics) has also shown good efficacy in reducing retinal inflammation and neovascularization in uveitis and CNV animal models." (PMID 37629185, 2023).
vitiligo (1 paper, 2011). Generalized well circumscribed patches of leukoderma that are generally distributed over symmetric body locations and is due to autoimmune destruction of melanocytes. "This study provides evidence that the CNV of C4, C4A or C4B may associate with the development of GD and <2 copies of C4A may associate with development of vitiligo in patients with GD." (PMID 21943165, 2011). "What is interesting is that although we explored the relationship of C4 CNV to GD as well as other GD clinical features, only the lower copies of C4A, but not C4B, were associated with higher risk of vitiligo." (PMID 21943165, 2011).